SEC22B (SEC22 homolog B, vesicle trafficking protein)
Description:
SNARE involved in targeting and fusion of ER-derived transport vesicles with the Golgi complex as well as Golgi-derived retrograde transport vesicles with the ER.
Synonyms: ERS-24; SEC22L1
Tractability: Antibody: UniProt predicts a signal peptide or a membrane-spanning region. PROTAC: ubiquitination databases record sites on it; its protein half-life has been measured.
Gene: Protein-coding gene on chromosome 1 (120,150,898 to 120,176,520, reverse strand). Ensembl gene ENSG00000265808.
Subcellular location: Endoplasmic reticulum membrane; Endoplasmic reticulum-Golgi intermediate compartment membrane; Golgi apparatus, cis-Golgi network membrane; Golgi apparatus, trans-Golgi network membrane; Melanosome
Pathways (Reactome):
Vesicle-mediated transport: COPI-dependent Golgi-to-ER retrograde traffic; COPII-mediated vesicle transport; Cargo concentration in the ER
Immune System: ER-Phagosome pathway
Gene Ontology:
Molecular function: protein binding; SNAP receptor activity
Biological process: negative regulation of autophagosome assembly; positive regulation of protein catabolic process; cellular response to starvation; endoplasmic reticulum to Golgi vesicle-mediated transport; macroautophagy; vesicle fusion; retrograde vesicle-mediated transport, Golgi to endoplasmic reticulum; vesicle-mediated transport
Cellular component: endoplasmic reticulum-Golgi intermediate compartment; ER to Golgi transport vesicle membrane; melanosome; autophagosome membrane; endoplasmic reticulum membrane; endoplasmic reticulum-Golgi intermediate compartment membrane; Golgi membrane; lysosomal membrane; phagocytic vesicle membrane; transport vesicle; cytoplasm; endomembrane system; Golgi apparatus; membrane
Genetic constraint (gnomAD): Loss-of-function variants: 3 observed, 3.25 expected, observed/expected ratio (o/e) 0.92, 90% interval 0.4 to 1.83. That is too few expected variants to judge how well the gene tolerates losing a copy. Missense variants: 34 observed, 35.59 expected, observed/expected ratio (o/e) 0.96, 90% interval 0.73 to 1.27. Synonymous variants: 16 observed, 16.62 expected, observed/expected ratio (o/e) 0.96, 90% interval 0.65 to 1.46.
Homologues: Orthologues: guinea pig SEC22B (100% identical), macaque SEC22B (100% identical), mouse Sec22b (100% identical), rat Sec22b (100% identical), pig SEC22B (99% identical), rabbit SEC22B (97% identical), tropical clawed frog sec22b (93% identical), zebrafish sec22bb (90% identical), zebrafish sec22ba (85% identical), Drosophila melanogaster Sec22 (56% identical), Caenorhabditis elegans sec-22 (47% identical). Paralogues in human: SEC22A (38% identical), SEC22C (30% identical), YKT6 (17% identical), VAMP4 (15% identical), VAMP7 (15% identical), VAMP1 (13% identical), VAMP2 (12% identical), VAMP3 (10% identical), VAMP8 (9% identical), VAMP5 (7% identical).
Diseases named in the same sentence as SEC22B in open-access papers:
SEC22B is named in the same sentence as 21 diseases in open-access papers, as found by Europe PMC text mining. Sharing a sentence is not in itself a finding about the gene and the disease. The quoted sentences say what the papers report.
Alzheimer disease (2 papers, 2018 to 2022). A progressive, neurodegenerative disease characterized by loss of function and death of nerve cells in several areas of the brain leading to loss of cognitive function such as memory and language. "Furthermore, the ER protein Sec22b promotes efficient membrane fusion in both anterograde and retrograde transport, and mutation of Sec22b has been implicated in atherosclerosis and Alzheimer's disease (AD)." (PMID 36129576, 2022). "Gene SEC22B, regulated by mir-206, has been identified to play a role in the progression and development of Alzheimer’s disease." (PMID 29621297, 2018).
breast carcinoma (2 papers, 2022). "The gene fusion of SEC22B confirmed in aggressive breast cancers and mantle cell lymphoma." (PMID 35057823, 2022). "Interestingly, the fusion of SEC22B-NOTCH2 activates the NOTCH pathway to the proliferation and survival of tumor cells in aggressive breast cancers and mantle cell lymphoma." (PMID 35038288, 2022).
Legionella infection (2 papers, 2020 to 2023). "In addition, it has been demonstrated that deubiquitination of Sec22b by LotB/Ceg23 during Legionella infection causes disassociation of Stx3 from Sec22b on LCVs, indicating that the ubiquitination status of Sec22b may be important for promoting this noncanonical pairing." (PMID 37882795, 2023). "The results revealed three up-regulated genes (SEC22B, CXCL2, and CYCS) and two down-regulated genes (CA3, CA4) were significantly involved in Legionellosis and nitrogen metabolism pathways, respectively." (PMID 32174961, 2020). "Legionella infection stimulates noncanonical pairing between Sec22b and PM-derived t-SNAREs, which is critical for the fusion of ER-originated vesicles with the bacterial phagosome." (PMID 37882795, 2023).
Cerebral ischemia (1 paper, 2022). Restriction of arterial blood supply to the brain associated with insufficient oxygenation to support the metabolic requirements of the tissue. "In this study, we found that cerebral ischemia induces neuronal autophagy, while reperfusion damages the integrity of autophagic flux, and Sec22b and Ykt6 are involved by regulating axonal autophagosome transport." (PMID 35654605, 2022).
esophageal cancer (1 paper, 2025). A primary or metastatic malignant neoplasm involving the esophagus. "Subsequently, proteomic data from 124 EC patients were used to analyze the relationship between RPN1 and SEC22B protein expression and the prognosis of esophageal cancer." (PMID 41203639, 2025). "We explored the expression of RPN1 and SEC22B in esophageal cancer." (PMID 41203639, 2025).
ischemic stroke (1 paper, 2022). A stroke disorder caused by obstruction of blood flow to the brain, due to thrombotic (local blood clot formation) or embolic (due to a blood clot or other material traveling from another site) event. "Thus, Sec22b and Ykt6 play key roles in neuronal autophagic flux, and modest regulation of Sec22b and Ykt6 may help to reverse the failure of targeting autophagy induction to improve the prognosis of ischemic stroke." (PMID 35654605, 2022).
lung carcinoma (1 paper, 2022). "Herein, we clarified the effects of autophagy and Sec22b status by analyzing lung cancer patient specimens as well as an online TCGA big database." (PMID 36457117, 2022). "Under starvation conditions, silencing of Sec22b expression in lung cancer H460 cells decreased TIMP1 secretion." (PMID 36457117, 2022). "The significance of secretory autophagy-related proteins p62 and Sec22b in lung cancer patient specimens as well as in an online big database were analyzed." (PMID 36457117, 2022). "We analyzed four tissue arrays of lung cancer patient specimens and an online lung cancer patient database to evaluate p62 and Sec22b protein levels." (PMID 36457117, 2022). "We also investigated the Sec22b protein level in the same set of lung cancer patient specimens." (PMID 36457117, 2022). "We further detected colocalization of LC3 with either Rab37 or TIMP1, identified Rab37 and Sec22b proteins in the purified autophagosomes of the lung cancer cells harboring the active-form Rab37 gene, and confirmed that these proteins are involved in the secretion of TIMP1." (PMID 36457117, 2022). "The effects of Sec22b on Rab37 and autophagy-mediated TIMP1 secretion and tumorigenesis in lung cancer H460 cells." (PMID 36457117, 2022). "Our findings imply that autophagy together with Sec22b plays a pivotal role in Rab37-mediated TIMP1 secretion and tumorigenesis of lung cancer cells." (PMID 36457117, 2022).
ovarian carcinoma (1 paper, 2022). A malignant neoplasm originating from the surface ovarian epithelium. "Interestingly, two candidate genes (SEC22B and FEZ2), which were highly associated with ovarian cancer in three cancer databases, were identified in the term “selective autophagy”." (PMID 35038288, 2022).
ovarian tumor (1 paper, 2024). "In addition, it has been reported that deubiquitination of Sec22b by LotB, an ovarian tumor-related proteases (OTU) family DUB, stimulates the dissociation of STX3 from Sec22b, suggesting that Sec22b ubiquitination is required for such an interaction." (PMID 38836877, 2024).
parasitemia (1 paper, 2023). "In this work, we show that Sec22b−/− mice elicit a deficient specific CD8+ T cell response when challenged with sublethal doses of Trypanosoma cruzi trypomastigotes that is associated with increased blood parasitemia and diminished survival." (PMID 36936692, 2023). "Conversely, Sec22b+/+ mice, that spontaneously controlled parasitemia, survived during the time studied (up to 60 days)." (PMID 36936692, 2023). "Furthermore, Sec22b−/− mice showed increased parasitemia than Sec22b+/+ (littermate controls), and lost weight until they finally died, while 100% of Sec22b+/+ mice survived at the time analyzed." (PMID 36936692, 2023).
Viral infection (1 paper, 2023). "To assess whether viral infection with SARS-Cov2 alters the pH of the ERGIC lumen, we fused the ERGIC transmembrane protein Sec22b to the ratiometic pH reporter probe pHluorin (Sec22b–rpHlu)." (PMID 36807531, 2023). "Viral infection did not alter the expression levels and subcellular distribution of the Sec22b–rpHluorin probe." (PMID 36807531, 2023).
tumor (8 papers, 2017 to 2026). "This study delineates a previously unrecognized axis of radiation-induced immune evasion in ESCC, revealing that radiotherapy triggers tumor-derived EVs to deliver lncRNA DYNLL1-AS1 that reprograms macrophage PD-L1 expression via SEC22B/FOXP1 signaling." (PMID 41522343, 2026). "Mice with Sec22b conditionally silenced in dendritic cells (Sec22b−/−) show deficient priming of CD8+ T lymphocytes, fail to control tumor growth, and are resistant to anti-checkpoint immunotherapy." (PMID 36936692, 2023). "About 65% of the tumor tissue showed positive Sec22b expression, and 71% of the non-tumor parts showed positive Sec22b expression." (PMID 36457117, 2022). "Successful outcomes following anti-PD-1 therapy require DC-T cell crosstalk and the initiation of anti-tumor CD8+ T cell responses by Sec22b-dependent cross-presentation in DCs." (PMID 30979057, 2019). "“To address the possible role of Sec22b-dependent antigen cross-presentation in tumor immunotherapy by checkpoint blocking antibodies, we used a less-immunogenic tumor, OVA-secreting MCA-101." (PMID 29449310, 2018). "It is interesting to note that mTOR, TFEB, and molecules involved in intracellular protein trafficking such as Sec22b are found in tumor-derived MVs." (PMID 28993771, 2017). "As expected, treatment with anti–PD-1 induced tumor rejection in Sec22b+/+ littermates." (PMID 29449310, 2018). "Sec22b−/− and Sec22b+/+ mice were injected with tumor cells and received or did not receive anti–PD-1 treatment." (PMID 29449310, 2018). "In contrast, Sec22b−/− mice failed to respond to anti–PD-1 treatment, both in terms of tumor growth and survival." (PMID 29449310, 2018). "Recently, Sec22b, a SNARE family member modulating the protein trafficking from ER to the endocytic and phagocytic pathways, has been shown to play a crucial role in antigen cross-presentation for effective anti-tumor immunity in vivo." (PMID 28993771, 2017).
infection (5 papers, 2020 to 2024). The state of being infected such as from the introduction of a foreign agent such as serum, vaccine, antigenic substance or organism. "In support of this hypothesis, we observed a significant increase in the association of Stx3 with ubiquitinated Sec22b in our biochemical as well as infection experiments." (PMID 37882795, 2023). "Sec22b colocalization was observed on approximately 65% of LCVs containing WT bacteria at 2 h post-infection." (PMID 37882795, 2023). "We thus aimed to characterize the Sec22b−/− mouse line in the context of the infection with T. cruzi, and thereby to contribute to the study of the role of XPt during this parasitic infection." (PMID 36936692, 2023). "Infection of host cells with the Δlug15 mutant significantly reduces but not abolishes the level of ubiquitinated Sec22b, suggesting that Sec22b is targeted by multiple Legionella E3s including Lug15." (PMID 37882795, 2023). "The resulting CHC22 downregulation significantly compromised recruitment of Sec22b to the bacterial vacuole 1 h after infection, suggesting defective vacuole maturation." (PMID 31863584, 2020). "Infection-stimulated ubiquitination of Sec22b appears to be important for the unconventional pairing event since deubiquitination of Sec22b by LotB could disassociate STX3 from Sec22b." (PMID 38836877, 2024). "Although two main pathways of XPt have been described—cytosolic and vacuolar –, here we demonstrate that the cytosolic Sec22b dependent-XPt plays a critical role in the activation of CD8+ T cells, an important branch of the immune response against the infection caused by T. cruzi in mice and humans." (PMID 36936692, 2023). "This deficient infection control is associated with a clear reduction in the priming of early specific CD8+ T cell responses in secondary lymphoid organs, although in lymph nodes the CD8+ T cell response finally reaches similar values in both Sec22b−/− and Sec22b+/+ mice at day 13 pi." (PMID 36936692, 2023). "Indeed, our recent study revealed that Lug15, a novel L. pneumophila E3 ligase, is responsible for Sec22b ubiquitination during infection and promotes the noncanonical interaction between STX3 and Sec22b." (PMID 38836877, 2024).
cancer (4 papers, 2020 to 2022). A tumor composed of atypical neoplastic, often pleomorphic cells that invade other tissues. "Several studies have reported that SEC22B is highly related to tumorigenesis that the mutations in SEC22B were found in various cancers." (PMID 35038288, 2022). "Moreover, its homolog SEC22B (SEC22 homolog B, vesicle trafficking protein) is involved in carcinogenesis and harbors several mutations associated with different cancer models." (PMID 33371395, 2020).
bacterial infection (1 paper, 2023). "Sec22b, the ER-associated v-SNARE protein, has long been known to be recruited to the LCV soon after bacterial infection." (PMID 37882795, 2023). "How ubiquitination induced by Lug15 impacts noncanonical SNARE pairing and how it coordinates with LotB/Ceg23 to impose temporal regulation of Sec22b function during bacterial infection require further investigation." (PMID 37882795, 2023).
SEC22B also shares sentences with these, for which no sentence is quoted: mantle cell lymphoma (2 papers); acute myeloid leukemia (1); atherosclerosis (1); infarction (1); infectious disease (1); Stroke (1).